IL6 (interleukin 6)
Diseases named in the same sentence as IL6 in open-access papers (continued):
Sharing a sentence is not in itself a finding about the gene and the disease.
bacterial infection (continued). "M1 activation, as induced by viral and bacterial infections, is characterized by the production of ROS and proinflammatory mediators, such as IL-1β (interleukin one beta), TNF-α (tumor necrosis factor alpha) and IL-6 (interleukin 6), which provide a robust microbe-killing activity." (PMID 35431927, 2022). "Nevertheless, elevated IL-6 activity has been observed in hepatic cell recovery following liver transplantation as well as in cases of early allograft dysfunction, rendering this proinflammatory biomarker rather nonspecific for bacterial infections." (PMID 35883545, 2022). "Upon activation by harmful stimuli such as cigarette smoke and bacterial infections, AMs release inflammatory mediators including nitric oxide (NO), prostaglandin E2 (PGE2), and pro-inflammatory cytokines such as tumor necrosis factor-α (TNF-α) and interleukin-6 (IL-6)." (PMID 35631552, 2022). "A single IL-6 level is not enough to predict the type of bacterial infection in all populations." (PMID 35432366, 2022). "After 2 days of surgery, the IL-6 (P < 0.0001), Gran (P = 0.0257), and WBC (P = 0.059) levels of the GNs + MV group were significantly lower than that the Ctrl group, indicating that the bacterial infection was restrained in the GNs + MV group due to the synergistic treatment of GNs and MV." (PMID 35513402, 2022). "During the early phase of bacterial infection, NK cells mainly produce interferon-γ (IFN-γ), which can prime macrophage activation and contribute to potent innate immune responses, including the secretion of tumor necrosis factor α (TNF-α), interleukin 6 (IL-6) and interleukin 1β (IL-1β)." (PMID 33327533, 2020). "Many of the highly expressed genes encode important factors of the innate immunity such as IL-1A, IL-6, IL-23A, TNF superfamily proteins, CCL and CXCL chemokine families and NFκB and STAT4 regulators and belong to common expression pattern mounted by host cells upon bacterial infection." (PMID 32070192, 2020). "As IL-6 activates transcription factor STAT3 to initiate the expression of other inflammatory factors, we studied whether Lyn regulates STAT3 in AMs during bacterial infection." (PMID 29263906, 2016). "Thus, it appears that IL-6 plays an important role in the long lasting negative impact of both viral and bacterial infection during prenatal period." (PMID 27445700, 2016). "Interestingly, compared with controls, piperine-administered mice had significant higher IL-6 and TNF-α levels in their peritoneal cavity lavage fluids at 6 h but had lowered levels of these cytokines at 24 h after bacterial infection, accompanied with a declined bacterial burden at 24 h." (PMID 26439699, 2015). "We repeated this analysis considering only the 31 patients with proven bacterial infection: IL-6 (p = 0.03), IL-8 (p = 0.02) were significantly raised in these patients compared to those without bacterial infection, while IL-17 (p = 0.02) was significantly decreased in the former." (PMID 22220196, 2011). "The two bacterial infections could be distinguished from IAV infection by weaker induction of type I and type II IFN signaling, but stronger enrichment of signaling pathways such as IL2_Stat5_signaling, IL6_STAT3 signaling, programmed cell death, and KRAS signaling (upregulated genes)." (PMID 39395995, 2024). "Additionally, we determined the serum levels of CRP and IL-6, as standard inflammation markers for assessing the systemic inflammatory response of the patients, and of PCT, as a parameter that helps to discriminate between bacterial and non-bacterial infections." (PMID 33903660, 2021). "Moreover, inflammatory mediators such as IL-6 and TGF-β are known to induce the development of TH17 cells and inhibit differentiation of regulatory T cells (Treg), which may also promote protection against extracellular bacterial infections." (PMID 29390040, 2018).
bacterial infection (continued). "Therefore, the increased PCT levels documented in HFRS patients may be resulted from the stimuli by elevated TNF-α and IL-6 even in the absence of bacterial infection." (PMID 29868489, 2018). "The fact that surgical intervention leads to induction of PCT by upregulation of proinflammatory cytokines such as tumor necrosis factor-(TNF-) a, Interleukin-1beta, or IL-6 may explain slight initial increase of postoperative values in absence of bacterial infection." (PMID 23766566, 2013). "Taken together, our findings indicate that in the absence of bacterial infection, corrector molecules can reduce the inflammatory profile of CFBE-F508del cells by selectively downregulating the production and secretion of IL-6 and IL-17A." (PMID 41487515, 2025). "Serum cytokines including IL‐1β, IL‐2, IL‐5, IL‐6, IL‐8, IL‐12 p70, IL‐17, and TNF‐α were significantly higher in COVID‐19 patients with bacterial coinfections than those without bacterial infection." (PMID 39692539, 2024). "There was a statistically significant difference in CRP (p = 0.014), PCT (p < 0.0001), IL-6 (p = 0.007), and WBC (p = 0.024), but not in temperature (p = 0.216), between the CAP-only and No Bacterial Infection groups." (PMID 38391578, 2024). "WBC, CRP and IL-6 have a lack of specificity, and PCT is mainly used to determine if a bacterial infection is present and to guide the use of antibiotics." (PMID 37158819, 2023). "In contrast, bacterial infection, irrespective of the type of bacteria i.e., AIEC or E. coli strain K-12, induced an increased release of IL-6 in the supernatants of MDM regardless of their origin (p < 0.0001 for each of them)." (PMID 31694333, 2019). "As evidenced by the reduction in supernatant levels of IL-6, TNF-α, and IL-23 from CD2-a infected macrophages compared to bacterial infection without Dex, glucocorticoids appear to affect inflammatory cytokine secretion." (PMID 29867993, 2018). "As expected, bacterial infection greatly increased the expression of IL-6 and TNF-α in their peritoneal cavity, whereas such cytokine levels were lower or undetectable without bacterial infection." (PMID 26439699, 2015). "In addition, plasma IL-1β and IL-6 were largely elevated in lactating sows by dietary intake of fish oil in the current study, which may be caused by the increase in MDA production instead of bacterial infection, as plasma CRP in lactating sows was not significantly influenced by fish oil intake." (PMID 40005899, 2025). "With regard to bacterial infections and rodent lines, one recent study reported that S. aureus can infect mouse 3T3-L1 cells and stimulate MCP-1 and IL-6 production, although there was no attempt to determine what S. aureus factors were involved in this response." (PMID 24205055, 2013). "The lower expression of IL-6 in IPF could indicate less active inflammation and lack of bacterial infections." (PMID 22014187, 2011). "During bacterial infections, however, non-endocrine tissues such as adipocytes release large quantities of PCT into the bloodstream in response to immuno-inflammatory stimuli, including lipopolysaccharides (LPS), bacterial toxins, Interleukin-6 (IL-6), and Tumor Necrosis Factor α (TNF- α)." (PMID 40310334, 2025).
metabolic disorders (340 papers, 2009 to 2026). "Previous in vitro and animal studies are in favor of a mediating role of IL-6 in the association between metabolic disorders and Alzheimer's pathology." (PMID 40606939, 2025). "The buildup of abdominal fat promotes the release of adipokines, such as TNF-α and IL-6, activating signaling pathways associated with metabolic disorders." (PMID 40997104, 2025). "Interleukin-6 (IL6) is a pleiotropic cytokine implicated in metabolic disorders and inflammation, yet its precise influence on insulin secretion and glucose metabolism remains uncertain." (PMID 38667300, 2024). "In this context, a cytokine of particular interest is IL-6, which plays a pivotal role in the body’s inflammatory processes and has been implicated in various health conditions, including metabolic disorders and diseases associated with inflammation." (PMID 38542789, 2024). "Inflammatory reactions are triggered by the production of pro-inflammatory cytokines such as TNF-α IL-1β, and IL-6 which are linked in the development of a number of metabolic diseases." (PMID 36552644, 2022). "Third, myokine secreted by skeletal muscle fibers, such as IL-6 and irisin, has a strong biological effect on reversing metabolic disorder, and the decrease of skeletal muscle mass also causes the decrease of endocrine function." (PMID 33740914, 2021). "Circulating serum levels of pro-inflammatory mediators, such as interleukin (IL)-1β, IL-6, tumor necrosis factor-α, C-reactive protein, and matrix metalloproteinases, are associated with both PD and lipoprotein disorders in elderly individuals." (PMID 33138320, 2020). "Next, we assessed levels of cytokines (TNF-α, IL-1β, and IL-6) that have been implicated in both metabolic disease and AD pathogenesis." (PMID 32993686, 2020). "IL-6 is one kind of proinflammatory cytokine and is closely associated with many metabolic disorders." (PMID 33015093, 2020). "IL-6 is another factor with a dual function, and is related to metabolic disorders, however, IL-6 after exercise is associated with metabolic improvements." (PMID 31590286, 2019). "The article reviews the importance of IL-6 in cardiac metabolic homeostasis and possible underlying mechanisms, hoping to provide new insights into therapeutic potential of IL-6 in targeting cardiac diseases caused by metabolic disorder." (PMID 30134607, 2018). "LPS is a major factor in bacterial pathogenesis and can cause a series of inflammatory responses in the body, including the release of inflammatory factors such as TNFα, IL1β and IL6, causing a variety of inflammatory symptoms such as metabolic disorders, fever and circulatory disturbances." (PMID 38504633, 2024). "Furthermore, IL-6 has also been associated with metabolic disorders such as MetS and T2D, in which elevated levels of IL-6 have been observed in adipose tissue." (PMID 38610754, 2024). "The increased circulating IL-6 levels from contracting skeletal muscle may enhance insulin sensitivity, lipolysis, and fat oxidation, therefore reducing the risk of metabolic disorders." (PMID 36834025, 2023). "For this reason, IL-6 has been causally related to metabolic disease." (PMID 36135761, 2022). "Furthermore, in healthy populations, inter-individual variations in IL-6 and NF-kB DNA methylation from WBCs have been associated with risk factors for cardiovascular and metabolic disorders." (PMID 34869683, 2021). "The results of this study may be helpful for a better understanding of the pathogenic role of IL-6 in inflammatory and metabolic disorders after acute stroke." (PMID 34943061, 2021). "IL-6 is one of the most abundant cytokines associated with metabolic disorders." (PMID 30974824, 2019). "Chronic inflammation is a major cause of metabolic diseases, and olive oil’s phenolic compounds have been shown to have potent anti-inflammatory effects by lowering CRP, TNF-α, and IL-6 levels." (PMID 40136590, 2025).
metabolic disorders (continued). "Our study suggests that IL-6 plays a determinant role not only in the acute phase response but also in the clinical course of severe metabolic disorders such as DKA." (PMID 40005437, 2025). "At the pathway level, our observations are consistent with known pro-tumorigenic inflammatory mechanisms shared between metabolic disease and carcinogenesis, including IL-6, MIF, GALECTIN, and CXCL signaling." (PMID 41488617, 2025). "Future research should employ prospective cohort designs to systematically compare ALI with gold-standard inflammatory biomarkers, such as C-reactive protein (CRP) and interleukin-6 (IL-6), in metabolic disorders." (PMID 40395814, 2025). "For instance, L. paraplantarum CRL 2051 reduces the production of pro-inflammatory cytokines such as TNF-α and IL-6 in a mouse model of metabolic disorders, highlighting its potential as an immunomodulator." (PMID 40284825, 2025). "Overall, muscle-derived IL-6 plays a central role in the metabolic adaptations induced by exercise and represents a potential therapeutic target for metabolic diseases." (PMID 40648864, 2025). "Key cytokines involved include TNF‐α, IL‐6, and IL‐1β, which are pivotal in the interplay between metabolic disease, inflammation, and carcinogenesis." (PMID 40661794, 2025). "The aggravation of oxidative stress not only stimulates the release of IFN-γ from macrophages, but also induces the secretion of inflammatory factors such as IL-6 and IL-1β, ultimately leading to metabolic disorders in the intestinal mucosa." (PMID 40284675, 2025). "Last, although our human cohort data hinted at trends in directionality linking adipocyte IL-6 with clinical parameters of metabolic diseases, our cohort size is too small to make robust conclusions." (PMID 41277555, 2025). "IL-6 is considered pro-inflammatory and increased levels in the bloodstream can culminate in metabolic diseases." (PMID 38792922, 2024). "On other hand, the role of some inflammatory cytokines, such as IL6, in metabolic disease is both confusing and controversial." (PMID 38167327, 2024). "Increased serum levels of pro-inflammatory cytokines such as tumor necrosis factor-alpha (TNF-alpha) and interleukin-6 (IL-6) have been documented in patients with metabolic disorders." (PMID 38409315, 2024). "Connected with MyD88 and TLR signaling genes (TNF-α, IL-6, IL-12);Participates in metabolic disease(TGF-β1)." (PMID 39911236, 2024). "IL1β, IL6, and TNFα are cytokines that are well identified as the inflammation markers involved in the metabolic disease of fish." (PMID 38671834, 2024). "High levels of IL-1 and IL-6, found in chronic inflammatory or metabolic diseases, stimulate the synthesis of acute phase molecules in the liver, such as reactive C protein and fibrinogen." (PMID 39200151, 2024). "The results showed that decreased metabolic disorder in recipient mice was accompanied by a significant elevation of Th2-type cytokines, including IL-4, IL-5, IL-6, IL-10, and IL-13." (PMID 38195424, 2024). "At the same time, Allobaculum was shown to be negatively correlated with the pro-inflammatory cytokines TNF-α and IL-6, while Blautia can attenuate inflammatory and metabolic diseases, demonstrating that Allobaculum and Blautia have anti-inflammatory effects." (PMID 36673366, 2023). "High-fat diets (HFD) promote inflammatory markers such as IL-6, and TNF-α, and increase the risk of liver toxicity, leading to dysfunctional energy metabolism and causing metabolic disease and inflammation." (PMID 37231328, 2023). "This indicates that in patients with metabolic disorders, IL-18 plays a more significant role in the proliferation of the glandular epithelium than IL-6." (PMID 37847180, 2023). "In addition, prolonged anhepatic time could increase the risk of graft dysfunction and metabolic disorders, mainly due to the accumulation of cytokines (e.g., interleukin 6), metabolites and other toxicants, and finally deteriorated renal function and reduced patient survival." (PMID 37452094, 2023).
metabolic disorders (continued). "Increases in specific inflammatory markers such as IL-6 and TNF-α, which can alter insulin sensitivity by triggering insulin signaling pathways, appear to be associated with metabolic disorders." (PMID 37152739, 2023). "Some metabolic disease/T1D-related genes (interleukins 6 and 10; IL-6, IL-10) and pathways enriched by differentially methylated loci were identified." (PMID 37239377, 2023). "These cytokines, such as TNFα and IL-6, play a crucial role in the development of metabolic diseases." (PMID 37849923, 2023). "Excess adipose tissue increases the production of pro-inflammatory factors such as leptin, tumor necrosis factor-α, interleukin-6, and resistin which contribute to the development of various metabolic diseases." (PMID 35287586, 2022). "Elderly MHO population who eat a MedDiet and practice regularly PA are capable to modulate their production of inflammatory cytokines (CRP, IL-6, TNFa) and adipokines profile (adiponectin, resistin), preventing other metabolic disorders." (PMID 35679338, 2022). "The previous studies also revealed that PIC has a therapeutic role especially in metabolic disorders like antioxidant (through lowering ROS), anti-inflammatory (through lowering IL-6, TNF-α), and by suppressing the cytokine signaling pathways." (PMID 35330107, 2022). "Adipose tissues secrete many inflammatory cytokines such as tumor necrosis factor α (TNF-α) and interleukin 6 (IL-6), which are a group of major contributing factors to metabolic disorders." (PMID 36141228, 2022). "As a transcription factor, NF-κB plays a critical role in various inflammatory-associated metabolic diseases, and its activation induces the production of proinflammatory cytokines TNF-α, IL-1β and IL-6." (PMID 36139325, 2022). "Metabolic disorders associated with chronic diseases and inflammation were demonstrated by a high concentration of pro-inflammatory markers such as TNF-α, MCP-1 and IL-6, and a decrease in anti-inflammatory factors such as adiponectin." (PMID 36235241, 2022). "The most significant hub gene identified in our study was IL6, which exerts pleiotropic roles in inflammation and metabolic diseases." (PMID 35894174, 2022). "It has been shown to aggravate inflammation and promote IL-6 secretion, which in turn, leads to metabolic disease." (PMID 35329121, 2022). "The pleiotropic inflammatory cytokine IL-6 plays a number of roles in inflammation and metabolic disease." (PMID 36290210, 2022). "As for IL-6 (pro- and anti-inflammatory cytokine), is a very interesting, pleiotropic cytokine with complex roles in inflammation and metabolic disease." (PMID 34066341, 2021). "Recent studies have also found that IL-6 has an inflammatory regulatory effect on SGAs-induced metabolic disorders." (PMID 33774704, 2021). "Metabolic disorders modeled by the HFD significantly altered the IL-6 content in muscle tissue under regular treadmill training." (PMID 34858197, 2021). "IL-6 plays a vital role in regulating immune diseases, infections, and metabolic diseases (Rose-John S., 2018." (PMID 34807222, 2021). "This dysfunction promotes metabolic disorders via a mild, chronic inflammation which is characterized by an increased expression of pro-inflammatory factors such as leptin, TNFα, IL6 or monocyte chemoattractant protein-1 (MCP-1 — also known as CCL2)." (PMID 34646852, 2021). "Prevotella predominantly stimulates cells to produce IL-1, IL-6, and IL-8, resulting in metabolic disorders and low-grade systemic inflammation." (PMID 32751062, 2020). "As the adipose cells increase in number and size, they start to produce a series of compounds that regulate metabolism, such as peptides and cytokines IL-6 and TNF-α, associated with numerous metabolic disorders." (PMID 31861497, 2019).